ASIC3 (acid sensing ion channel subunit 3)
Diseases named in the same sentence as ASIC3 in open-access papers (continued):
Sharing a sentence is not in itself a finding about the gene and the disease.
multiple myeloma (2 papers, 2021 to 2025). "Interestingly, a selective ASIC3 antagonist, APETx2, was able to markedly reduce bone pain in a murine intratibial multiple myeloma model and decreased excitability of DRG neurons cocultured with human multiple myeloma cells, providing functional evidence for the role of ASIC3." (PMID 33981921, 2021).
osteoporosis (2 papers, 2019 to 2022). A condition of reduced bone mass, with decreased cortical thickness and a decrease in the number and size of the trabeculae of cancellous bone (but normal chemical composition), resulting in increased fracture incidence. "Acid-sensing ion channel 3 (ASIC3) plays a crucial role in the secondary hyperalgesia of joint inflammation in OA rats, as it does in osteoporosis, but not in primary hyperalgesia." (PMID 36012312, 2022).
vasculitis (2 papers, 2009 to 2021). "Also, the proportion of vessels affected by vasculitis seemed to be higher in ASIC3+/+ mice than in ASIC3-/- mice (69.02% vs. 31.13% P < 0.05)." (PMID 19126241, 2009).
atopic dermatitis (1 paper, 2023). "Although ASIC3 is considered to contribute to dry skin-induced itch, this is the first report of ASIC3 activation playing a role in atopic dermatitis associated itch." (PMID 36937045, 2023). "Finally, we identified significantly higher levels of agmatine in the affected skin of a mouse model of atopic dermatitis (AD) when compared to controls, and the scratching behavior of AD mice was significantly attenuated by blocking ASIC3." (PMID 36937045, 2023).
brain injury (1 paper, 2019). Acute and chronic (see also brain INJURIES, CHRONIC) injuries to the brain, including the cerebral hemispheres, CEREBELLUM, and brain STEM. "The proportion of three ASIC3 genetic variants among mild traumatic brain injury (mTBI) and non-mTBI group." (PMID 30804886, 2019).
Cough (1 paper, 2017). A sudden, audible expulsion of air from the lungs through a partially closed glottis, preceded by inhalation. "This provides a possible mechanism of how virus infection causes hypersensitisation in the airways and indicates that TRPV1, TRPA1 and ASIC3, or upstream events leading to their activation, are potential therapeutic targets for the treatment of virus-induced cough." (PMID 28187208, 2017).
cystitis (1 paper, 2021). Inflammation of the urinary bladder. "Moreover, a common form of bladder irritation is cyclophosphamide-induced cystitis and in rats this is accompanied by increased ASIC3 expression in the urothelium and suburothelia plexus, but not in the detrusor smooth muscle, thus further suggesting a role for ASIC3 in bladder function." (PMID 33258401, 2021).
depression (1 paper, 2011). "Behaviors reduced by ASIC1a disruption but not by transgenic ASIC3 expression included unconditioned fear of predator odor and open spaces, CO2-evoked freezing behavior and depression-related behavior in the forced swim test." (PMID 21324060, 2011).
diabetic neuropathy (1 paper, 2021). A chronic, pathological complication associated with diabetes mellitus, where nerve damages are incurred due to diabetic microvascular injury involving small blood vessels that supply these nerves, resulting in peripheral and/or autonomic nerve dysfunction. "Considering the role of ASIC3 in pain and that lactate levels increase in response to elevated glucose levels (i.e. after meals), this may add to the potential for ASIC3 sensitization to contribute to pain in diabetic neuropathy." (PMID 33258401, 2021).
disc degeneration (1 paper, 2021). "There is therefore a positive correlation for ASIC1a, ASIC3 and NLRP3 with disc degeneration." (PMID 33111436, 2021).
gastroesophageal reflux disease (1 paper, 2022). A chronic disorder characterized by reflux of the gastric and/or duodenal contents into the distal esophagus. "Considering oesophageal heartburn pain associated with gastroesophageal reflux disease (GERD), ASIC1 and ASIC3 expression were recently found to be increased in biopsies of patients compared to healthy subjects, which positively correlates with symptom severity of heartburn and regurgitation." (PMID 36287977, 2022).
Headache (1 paper, 2018). Cephalgia, or pain sensed in various parts of the head, not confined to the area of distribution of any nerve. "When low pH is directly applied to the dura of awake animals, they display headache-related behaviors which can be blocked at lower pHs by amiloride or at higher pHs by APETx2 (natural venom toxin from the sea anemone Anthopleura elegantissima, an ASIC3 antagonist)." (PMID 29549622, 2018). "Additionally, a study in 2013 showed that ASIC3 is the predominant ASIC responding to a reduced meningeal pH and in the context of inflammation; dural afferents are responsive to even smaller pH changes within the meninges, suggesting a role in headache." (PMID 29549622, 2018).
itch (1 paper, 2023). "Collectively, these results provide evidence that agmatine is a novel mediator of itch and induces itch via the activation of ASIC3." (PMID 36937045, 2023). "In a word, we have provided strong evidence to indicate that agmatine is a novel mediator of itch and that ASIC3 is involved in agmatine-induced histamine-independent pruritus in mice." (PMID 36937045, 2023). "Furthermore, we found that ASIC3 was indispensable in agmatine-induced itch and the hyper-excitability of DRG neurons." (PMID 36937045, 2023). "Nevertheless, whether the subpopulation of neurons that are responsive to SL-NH2 via ASIC3 is the same to as that responsible for agmatine-induced itch has yet to be elucidated." (PMID 36937045, 2023). "Thus, our results suggest that ASIC3 signaling is critical for agmatine-induced itch and that targeting ASIC3 may serve as an important strategy for the treatment of chronic itch." (PMID 36937045, 2023).
lactic acidosis (1 paper, 2020). Metabolic acidosis characterized by the accumulation of lactate in the body. "Asic3, an acid channel and sensor for lactic acidosis is predicted to be elevated in Weddell seal muscles via downregulation of miR-206-3p." (PMID 32293246, 2020).
leukemia (1 paper, 2025). A malignant (clonal) hematologic disorder, involving hematopoietic stem cells and characterized by the presence of primitive or atypical myeloid or lymphoid cells in the bone marrow and the blood. "Subsequent limiting dilution assays with YFP+ leukemia cells from the primary transplant revealed that the LIC frequency was 1 in 11 of Asic3-null leukemia cells, which was approximately 9-fold higher than that in WT control cells (n = 1 in 93 cells)." (PMID 41392978, 2025). "To verify the changes of STIM1-mediated calcium signaling during leukemia development, we measured constitutive capacities of calcium influx in Asic3-null leukemia bulk cells or LICs." (PMID 41392978, 2025). "More importantly, silencing ASIC3 in THP-1 or U937 cells significantly increased the frequency of leukemia cells in the PB and markedly reduced the survival of NOD-SCID mice compared with their counterparts." (PMID 41392978, 2025). "Consistently, an in vitro surrogate functional analysis with methylcellulose medium revealed a significant increase in colony size, colony number, and total cell number of Asic3-null leukemia cells during both first and second platings." (PMID 41392978, 2025). "Thus, we examined the protein levels of CREB in Asic3-null YFP+ BM leukemia cells by immunoblotting, which showed that both phosphorylated and total CREB levels were markedly increased." (PMID 41392978, 2025). "Identification of additional ligands for ASIC3 may be beneficial for understanding ASIC3’s role in leukemogenesis and the development of strategies for leukemia treatment." (PMID 41392978, 2025). "We measured MEIS1 protein levels in both LICs and the bulk of BM leukemia cells, using Western blotting, and found that the MEIS1 levels were substantially increased in Asic3-null AML cells, especially in Asic3-null LICs." (PMID 41392978, 2025). "In this study, we show that an acidic niche can activate ASIC3-mediated noncanonical signaling independent of its channel function in both mouse and human LICs to inhibit leukemia development." (PMID 41392978, 2025). "The constitutive calcium influx was significantly reduced at pH 7.0 in either WT leukemia bulk cells or LICs, but not in Asic3-null cells." (PMID 41392978, 2025). "The accelerated leukemia development also resulted in a more severe infiltration in spleens and livers upon Asic3 (but not Asic1a) deletion (other data not shown)." (PMID 41392978, 2025). "Because CAMK1 activity is tightly regulated by the calcium signaling, we sought to understand how calcium signaling was affected by Asic3 deletion and found that the STIM1 level, a key mediator of calcium influx, was notably increased in LICs, as well as in YFP+ BM leukemia cells." (PMID 41392978, 2025). "Importantly, in our AML model, the STIM1-ASIC3 N-terminal interaction appears to play a dominant role in regulating downstream calcium signaling and leukemia cell behavior, regardless of extracellular pH or ASIC3 conductance." (PMID 41392978, 2025). "Intriguingly, by using an MLL-AF9–induced AML model with Asic1a–/– and Asic3–/– mice, we observed that the frequencies of Asic3-null, but not Asic1a-null, leukemia cells in the peripheral blood (PB) were significantly higher than those in control mice upon primary transplantation." (PMID 41392978, 2025). "More importantly, the overall survival of primary recipients receiving Asic3-null leukemia cells, but not Asic1a-null cells, was significantly reduced, indicating that ASIC3 may suppress leukemogenesis." (PMID 41392978, 2025).
lung adenocarcinoma (1 paper, 2022). A carcinoma that arises from the lung and is characterized by the presence of malignant glandular epithelial cells. "Bioinformatic analysis of the gene expression in the tissues from the patients with lung adenocarcinoma revealed possible implications of ASIC1, ASIC2, ASIC3, ASIC4, α-ENaC, and γ-ENaC in the disease progression." (PMID 35837090, 2022).
malaise (1 paper, 2025). A feeling of general discomfort or uneasiness, an out-of-sorts feeling. "Notably, upregulation of purinergic receptors (P2 × 4, P2 × 5), transient receptor potential vanilloid 1 (TRPV1), and acid-sensing ion channel 3 (ASIC3) has been associated with post-exertional malaise." (PMID 41057909, 2025).
myeloid leukemia (1 paper, 2025). A clonal proliferation of myeloid cells and their precursors in the bone marrow, peripheral blood, and spleen. "To further examine whether ASIC3 plays a specific role in AML, we used an alternative myeloid leukemia model driven by AML1-ETO9a, a splice variant of AML1-ETO." (PMID 41392978, 2025).
pressure ulcer (1 paper, 2020). "The acid-sensing ion channel 3 (Asic3), a neuronal sensor is known to play a pivotal role in causing the vasodilatory response to direct pressure and also for protecting against pressure ulcer." (PMID 32528410, 2020).
psoriasis (1 paper, 2024). An autoimmune condition characterized by red, well-delineated plaques with silvery scales that are usually on the extensor surfaces and scalp. "The ASIC3 knockdown also lessened production of psoriasis-related cytokines, mainly IL-17, IL-22, and IL-23." (PMID 38902277, 2024). "Our results suggest that silencing ASIC3 interrupts the pro-inflammatory signaling loop between neural and immune systems, providing evidence for a potential neuroimmune strategy to treat psoriasis and other cutaneous inflammatory diseases." (PMID 38902277, 2024). "In conclusion, our study unveils novel insights into the mechanism governing neuroimmune interactions in psoriasis, emphasizing the therapeutic potential of targeting ASIC3 in chronic inflammatory skin diseases." (PMID 38902277, 2024). "To assess the contribution of TRPV1+ nociceptors in ASIC3-dependent skin inflammation in the mouse psoriasis model, we treated Asic3+/+ and Asic3−/− mice with resiniferatoxin (RTX)." (PMID 38902277, 2024). "The conditional rescue of ASIC3 in NaV1.8Cre mice led to more severe epidermal thickening and Ki67 cell proliferation, as well as higher production of psoriasis-related cytokines, IL-17, IL-22, and IL-23, compared to the ASIC3 knockdown mice." (PMID 38902277, 2024). "Thus, the loss of ASIC3 in mice is as effective as nociceptor ablation in ameliorating psoriatic inflammation, underscoring the unequivocal functional significance of ASIC3 in TRPV1+ nociceptors in psoriasis pathogenesis." (PMID 38902277, 2024). "Interestingly, re-expression of ASIC3 solely in NaV1.8+ nociceptors aggravated splenomegaly in the psoriasis model." (PMID 38902277, 2024). "This denervation treatment of TRPV1+ nociceptive terminals significantly reduced splenomegaly of the IMQ-treated Asic3+/+ mice, indicating that TRPV1+ nociceptive innervation regulates the global inflammatory response in psoriasis." (PMID 38902277, 2024). "However, in Asic3−/− mice, the chemical denervation of TRPV1+ nociceptors failed to further alleviate splenomegaly in the psoriasis model, arguing for the essential role of ASIC3 in the TRPV1+ nociceptor-mediated regulation." (PMID 38902277, 2024).
synovitis (1 paper, 2014). Inflammation of a synovial membrane. "Taken together these data support a protective role of ASIC3 under inflammatory conditions - activation of ASIC3 would cause cell death and limit synovitis." (PMID 24923411, 2014). "In synovitis, inflammatory mediators are released that can activate intracellular pathways to increase expression of ASIC3, decrease expression of ASIC1, increase (Ca2+)i, and increase phosphorylation of ERK." (PMID 24923411, 2014). "Thus, decreases in pH under inflammatory conditions play a protective role by activating ASIC3 to limit synovitis and could be a potential new therapeutic target." (PMID 24923411, 2014).
tumor (14 papers, 2013 to 2026). "The higher expression of ASIC1/ASIC3 was associated with poor tumor differentiation, advanced TNM stage, lymph node metastasis and distant metastasis." (PMID 28518134, 2017). "The majority of cancer research has been on ASIC1, whereas the roles of ASIC2 and ASIC3 have been explored in only a limited number of studies, but they seem related to acidification of the tumor microenvironment." (PMID 41516419, 2026). "Additionally, ASIC3 has been identified as a contributor to GSC proliferation and migration, with its inhibition leading to reduced tumour growth, suggesting that ASIC3 is another promising target for therapy." (PMID 40806720, 2025). "Homomeric ASIC3 and heteromeric ASIC3-containing channels of the PNS are involved in the perception of pain associated with tissue acidosis caused by mechanical damage, inflammation, tumor, etc.." (PMID 32326130, 2020). "Future studies need to clarify the exact role of ASIC1 and ASIC3 in different tumours." (PMID 29057936, 2017). "In order to evaluate the effects of zoledronic acid and paclitaxel on spinal nerve activity, the mRNA levels of c-fos and TRPV1 in the ipsilateral spinal cord, and ASIC3 in the ipsilateral DRG were assessed on days 14 and 21 post-tumor cell inoculation." (PMID 26081451, 2015). "Bone marrow MSCs and fibroblasts are known to express high levels of acid sensing receptors [acid-sensing ion channel 3 (ASIC3), ASIC4, G protein-coupled receptor 4 (GPR4), and GPR65], and become activated by the acidic environment created by bone metastatic tumor cells." (PMID 29747461, 2018). "ASIC3 acts as a potent tumor suppressor to dramatically delay the leukemogenesis in a noncanonical manner, indicating that activation of ASIC3 may be an attractive way to target LICs." (PMID 41392978, 2025). "Some of these currents had kinetics typical for ASICs and were sensitive to specific toxin inhibitors of ASIC1a or ASIC3, demonstrating that the GBM cell lines express functional ASIC1a and ASIC3 that may enable GBM cells to sensitively detect extracellular pH in a tumour tissue." (PMID 29057936, 2017). "In addition, osteoclast- and tumour-induced acidosis in bone tissue may also contribute to the pathobiology of PCIBP by sensitizing subsets of sensory neurons that express the transient receptor potential vanilloid 1 (TRPV1) and/or the acid-sensing ion channel 3 (ASIC3)." (PMID 23918298, 2013). "The role of ASIC1 and ASIC3 was further confirmed in-vivo, where a xenograft mouse model injected with BxPC-3 cells with a stable knockdown of ASIC1 and ASIC3 showed a significant decrease in lung and liver metastasis, but no obvious effect on tumor growth." (PMID 33178018, 2020). "Separate inhibition or knockdown of ASIC1 and ASIC3 decreased the acidity-promoted invasion and migration capacity of PDAC cell lines, but did not decrease the proliferation rate, suggesting that ASIC1 and ASIC3 are involved in the metastatic process of PDAC, but not tumor cell growth." (PMID 33178018, 2020).
cancer (13 papers, 2015 to 2026). A tumor composed of atypical neoplastic, often pleomorphic cells that invade other tissues. "Recent studies reported that the tissue damage and inflammation caused by cancer greatly decreases the thresholds of TRPV1 and ASIC3 for sensing noxious stimulation." (PMID 30366393, 2018). "Compared with the cancer group and cancer with NS group, the mRNA levels of c-fos in the spinal cord and of ASIC3 in the DRG in the cancer with ZOL group were significantly reduced on days 14 and 21 post-inoculation (P<0.05)." (PMID 26081451, 2015). "Targeting ASIC3 may be an attractive way to eradicate LICs or other types of cancer stem cells." (PMID 41392978, 2025). "The relative mRNA levels of c-fos and TRPV1 in the ipsilateral spinal cord and of ASIC3 in the ipsilateral DRG in the cancer, cancer with NS, cancer with ZOL and cancer with TA groups were significantly increased, compared with the naive and sham groups (P<0.05)." (PMID 26081451, 2015).
infection (3 papers, 2014 to 2020). The state of being infected such as from the introduction of a foreign agent such as serum, vaccine, antigenic substance or organism. "We demonstrate here that the infection with MV and RSV in BEAS-2B epithelial and SHSY5Y neuronal cells induces significant up-regulation of TRPV1 and ASIC3 mRNA levels compared to mock-infected cultures." (PMID 28187208, 2017). "Our data show that the virus MOI and duration of infection are important factors in TRPV1 and ASIC3 expression modulation in both epithelial and neuronal cells." (PMID 28187208, 2017).
inflammation (2 papers, 2010 to 2012). Aberrant reaction of the microcirculation characterized by movement of fluid and leukocytes from the blood into extravascular tissues. "Our laboratory also showed an increase in the number of joint afferents that express ASIC3 after joint inflammation." (PMID 22191025, 2012).
cardiovascular diseases (1 paper, 2014). "In summary, we unraveled an important role of ASIC3 in regulating cardiac autonomic function, whereby loss of ASIC3 alters the normal physiological response to ischemic stimuli, which reveals new implications for therapy in autonomic nervous system-related cardiovascular diseases." (PMID 24804235, 2014). "We provided an in vivo evidence for ASIC3 in regulating cardiac autonomic function, whereby loss of ASIC3 alters the normal physiological response to ischemic stimuli, which reveals new implications for therapy in autonomic nervous system-related cardiovascular diseases." (PMID 24804235, 2014).
connective tissue disease (1 paper, 2022). "We found that the expression of ASIC3 mRNA was upregulated in cutaneous fibrotic connective tissue disease." (PMID 35661105, 2022).
metabolism disorders (1 paper, 2024). "Taken together, the findings suggest that PF could alleviate intestinal fluid metabolism disorders in STC rats by activating the ASIC3/ERK signaling pathway." (PMID 38634140, 2024).